BPNT2 (3'(2'), 5'-bisphosphate nucleotidase 2)
Description:
Exhibits 3'-nucleotidase activity toward adenosine 3',5'-bisphosphate (PAP), namely hydrolyzes adenosine 3',5'-bisphosphate into adenosine 5'-monophosphate (AMP) and a phosphate. May play a role in the formation of skeletal elements derived through endochondral ossification, possibly by clearing adenosine 3',5'-bisphosphate produced by Golgi sulfotransferases during glycosaminoglycan sulfation. Has no activity toward 3'-phosphoadenosine 5'-phosphosulfate (PAPS) or inositol phosphate (IP) substrates including I(1)P, I(1,4)P2, I(1,3,4)P3, I(1,4,5)P3 and I(1,3,4,5)P4.
Synonyms: gPAPP; IMPA3; IMPAD1; FLJ20421; IMP 3; IMP-3
Tractability: Antibody: UniProt predicts a signal peptide or a membrane-spanning region. PROTAC: ubiquitination databases record sites on it.
Gene: Protein-coding gene on chromosome 8 (56,957,931 to 56,993,867, reverse strand). Ensembl gene ENSG00000104331.
Subcellular location: Golgi apparatus; Golgi apparatus, trans-Golgi network membrane
Subcellular location (Human Protein Atlas): Golgi apparatus; Cytosol; Nucleoplasm
Pathways (Reactome):
Metabolism: Cytosolic sulfonation of small molecules
Gene Ontology:
Molecular function: 3'(2'),5'-bisphosphate nucleotidase activity; 3',5'-nucleotide bisphosphate phosphatase activity; 3'-nucleotidase activity
Biological process: skeletal system development; phosphatidylinositol phosphate biosynthetic process
Cellular component: Golgi apparatus; membrane; endomembrane system; Golgi lumen; trans-Golgi network membrane
Genetic constraint (gnomAD): Loss-of-function variants: 7 observed, 21.24 expected, observed/expected ratio (o/e) 0.33, 90% interval 0.19 to 0.62. The upper end of that interval is the gene's LOEUF score, 0.62, which puts it in group 2 of 6, group 1 being the genes least tolerant of losing a copy. Missense variants: 408 observed, 384.8 expected, observed/expected ratio (o/e) 1.06, 90% interval 0.98 to 1.15. Synonymous variants: 178 observed, 157.49 expected, observed/expected ratio (o/e) 1.13, 90% interval 1 to 1.28.
Gene-disease validity (ClinGen):
ClinGen rates the evidence that BPNT2 causes each of these diseases.
chondrodysplasia with joint dislocations, gPAPP type (autosomal recessive): Moderate.
Homologues: Orthologues: chimpanzee BPNT2 (100% identical), macaque BPNT2 (99% identical), dog BPNT2 (98% identical), pig BPNT2 (96% identical), rabbit BPNT2 (96% identical), guinea pig BPNT2 (94% identical), mouse Bpnt2 (91% identical), rat Bpnt2 (89% identical), tropical clawed frog bpnt2 (67% identical), Drosophila melanogaster CG17029 (15% identical), Drosophila melanogaster CG17028 (15% identical), Drosophila melanogaster CG17027 (14% identical), and 1 more. Paralogues in human: BPNT1 (25% identical), INPP1 (24% identical), IMPA2 (17% identical), IMPA1 (15% identical).
Diseases named in the same sentence as BPNT2 in open-access papers:
BPNT2 is named in the same sentence as 17 diseases in open-access papers, as found by Europe PMC text mining. Sharing a sentence is not in itself a finding about the gene and the disease. The quoted sentences say what the papers report.
chondrodysplasia (9 papers, 2019 to 2025). "Subsequent studies by other groups identified an autosomal recessive human disorder caused by mutations in BPNT2 and characterized by chondrodysplasia, reminiscent of the KO mouse phenotype, as well as other disorders of GAG sulfation." (PMID 34634304, 2021). "We also demonstrate that missense mutations in Bpnt2 adjacent to the catalytic site, which are known to cause chondrodysplasia in humans, recapitulate defects in overall GAG sulfation and chondroitin-4-sulfation in MEF cultures." (PMID 34634304, 2021). "We also evaluated two missense mutations in BPNT2 that are associated with chondrodysplasia in humans and are adjacent to the core catalytic motif." (PMID 34634304, 2021). "Interestingly, two missense mutations in Bpnt2 localized near this locus are known to cause chondrodysplasia in humans." (PMID 34634304, 2021). "We studied 3 Bpnt2 mutations, which happen to be in close proximity to the active site/metal-binding domain (one that ablates catalytic activity, two that are known to cause chondrodysplasia in humans)." (PMID 34634304, 2021). "IMPAD1/BPNT2 is localized to the golgi and autosomal recessive mutations in this gene have been shown to cause chondrodysplasia in humans." (PMID 37146074, 2023). "However, this decrease was not rescued by the expression of catalytic-dead Bpnt2 or chondrodysplasia-associated mutant Bpnt2." (PMID 34634304, 2021).
BPNT2 also shares sentences with these, for which no sentence is quoted: cancer (3 papers); lung carcinoma (3); skeletal dysplasia (3); breast carcinoma (2); Catel-Manzke syndrome (2); Desbuquois dysplasia 1 (2); glioma (2); amelogenesis imperfecta (1); Down syndrome (1); Ehlers-Danlos syndrome (1); genetic disorders (1); Larsen syndrome (1); lung adenocarcinoma (1); Marfan syndrome (1); multiple myeloma (1); tumor (1).